ERAS (ES cell expressed Ras)
Description:
Ras proteins bind GDP/GTP and possess intrinsic GTPase activity. Plays an important role in the tumor-like growth properties of embryonic stem cells (By similarity).
Synonyms: HRAS2; HRASP
Tractability: Antibody: UniProt places it where antibodies can reach, with medium confidence; its Gene Ontology location is reachable by antibodies, with medium confidence.
Gene: Protein-coding gene on chromosome X (48,826,513 to 48,830,138, forward strand). Ensembl gene ENSG00000187682.
Subcellular location: Cell membrane
Gene Ontology:
Molecular function: protein binding; GTPase activity; G protein activity; GTP binding
Biological process: positive regulation of cell population proliferation; Ras protein signal transduction; signal transduction
Cellular component: plasma membrane; membrane
Homologues: Orthologues: chimpanzee ERAS (100% identical), macaque ERAS (99% identical), pig ERAS (82% identical), dog ERAS (79% identical), mouse Eras (74% identical), rat Eras (71% identical). Paralogues in human: NRAS (39% identical), HRAS (38% identical), KRAS (37% identical), RRAS (34% identical), RRAS2 (32% identical), MRAS (31% identical), RIT1 (31% identical), RAP1B (31% identical), RAP1A (30% identical), RALB (30% identical), RIT2 (30% identical), RALA (29% identical), and 23 more.